DPP4 (dipeptidyl peptidase 4)
Diseases named in the same sentence as DPP4 in open-access papers (continued):
Sharing a sentence is not in itself a finding about the gene and the disease.
prostate carcinoma (55 papers, 2009 to 2026). A carcinoma that arises from epithelial cells of the prostate gland. "Despite this, high CD26/DPP-4 expression in prostate cancer is paradoxically associated with poor prognosis." (PMID 40282969, 2025). "Prostate cancer was associated with the most abundant expression of DPP4, followed by thyroid cancer, renal cancer, carcinoid, endometrial cancer, and lung cancer; DPP4 was ordinarily analyzed in CAB045970 database." (PMID 33614513, 2021). "A study showed that prostate cancer tissue with high DPP4 expression was associated with poor prognosis (p < 0.0001)." (PMID 34055551, 2021). "DPP4 as the composed gene of risk prediction models in prostate cancer, its expression is significantly related to multiple clinic-pathological factors and survival in our results." (PMID 33407865, 2021). "Due to these associations, DPP4/CD26 has been proposed as a potential tumor marker to predict clinical course in prostate cancer." (PMID 34055551, 2021). "Herein, we conducted a case–control study to evaluate whether single‐nucleotide polymorphisms (SNPs) of DPP4 were associated with the risk or clinicopathologic development of prostate cancer (PCa)." (PMID 37533175, 2023). "Single-cell sequencing analysis, virtual knockout analysis and TIDE analysis were conducted to validate the role of DPP4 in prostate cancer." (PMID 41909664, 2026). "In prostate cancer, DPP4 was markedly downregulated (p < 0.001) and higher expression predicted better overall survival (p < 0.001) and progression-free survival (p < 0.001)." (PMID 41909664, 2026). "Research has shown that prostate cancer cells exhibit elevated DPP-4 activity, potentially explaining the survival benefits observed in DPP-4i users." (PMID 40282969, 2025). "This study clearly demonstrates that Linagliptin, a well-known DPP-4 inhibitor, can regulate the progression of prostate cancer cells by modulating the PI3k/Akt pathway and its key genes, as illustrated in the schematic presentation." (PMID 40766751, 2025). "In sharp contrast to LE-1 and LE-2, LE-3 cells were specifically marked by DPP4 (Dipeptidyl peptidase 4), an AR-stimulated tumor suppressor in prostate cancer." (PMID 41468516, 2025). "When discussing the role of GLP-1 receptor agonists in the regulation of pathways influencing prostate cancer carcinogenesis, it is worth mentioning dipeptidyl peptidase 4 (DPP-4), which also regulates the activity of the ERK1/2- and mTOR-dependent pathway." (PMID 40361502, 2025). "Although DPP-4 is typically regarded as a pro-oncogene, it has been observed to play an anti-oncogenic role in certain tumors such as glioma and prostate cancer." (PMID 39390508, 2024). "Odds ratio (OR) and 95% confidence interval (CI) of the clinical status and DPP4 rs7608798 genotypic frequencies in 704 patients with prostate cancer." (PMID 37533175, 2023). "DPP4 inhibitors were shown to be effective, improving the survival rate in prostate cancer patients." (PMID 37185411, 2023). "Odds ratio (OR) and 95% confidence interval (CI) of the clinical status and DPP4 rs2268889 genotypic frequencies in 704 patients with prostate cancer." (PMID 37533175, 2023). "Studies40 have revealed high DPP4 expression in patients with prostate cancer, pancreatic cancer and BC." (PMID 37849388, 2023). "We then assessed the expression of DPP4 between subgroups in prostate cancer tissues, and found DPP4 expression in N1 was low than N0 (P < 0.001)." (PMID 33407865, 2021). "Additional analysis with larger sample sizes and prospective investigation with study of tumor microenvironment are needed to evaluate clinical impact and potential survival benefit of DPP4 inhibitors in prostate cancer." (PMID 34055551, 2021). "In this multi-center retrospective study, we aim to define the effects of DPP4 inhibitors on progression-free survival (PFS) in diabetic patients with advanced-stage prostate cancer." (PMID 34055551, 2021).
prostate carcinoma (continued). "The expression levels of DPP4 based on gleason score 9 group, N1 nodal metastasis group, and FOXA1 mutation group in prostate cancer tissues were lower than normal controls (all P < 0.001)." (PMID 33407865, 2021). "In the TCGA dataset, we found that DPP4 was highly expressed in renal cancer and prostate cancer, which was consistent with its expression in normal tissues." (PMID 33614513, 2021). "The lasso results also showed that five genes (AR, PDHA1, RAN, DPP4 and DAZAP1) were the powerful composed factors of prostate cancer risk prediction model." (PMID 33407865, 2021). "It is also the first study to our knowledge that directly compares the effects of metformin with DPP4 inhibitors in prostate cancer." (PMID 34055551, 2021). "Specifically, 24 of 41 (59%) patients on DPP4 inhibitors progressed, while 73 of 120 (61%) patients on metformin had progression of prostate cancer (HR: 1.01; 95% CI: 0.64-1.61; p = 0.955)." (PMID 34055551, 2021). "Recent literature has identified DPP4 inhibitors to improve survival in diabetic patients with prostate cancer." (PMID 34055551, 2021). "DPP4 inhibitors have been proposed to play a role in prostate cancer, as DPP4 is found at higher levels in malignant prostate tissue compared to benign and correlates with PSA levels and cancer stage." (PMID 34055551, 2021). "In this study, we examined the effect of DPP4 inhibitors on PFS in diabetic patients with advanced-stage prostate cancer." (PMID 34055551, 2021). "Further large-scale efforts are necessary to investigate the survival outcomes in patients with advanced prostate cancer on metformin versus DPP4 inhibitors." (PMID 34055551, 2021). "This study aims to further investigate the clinical impact of using DPP4 inhibitors in advanced prostate cancer using clinical data available at two tertiary referral cancer institutions." (PMID 34055551, 2021). "Another study using prostate cancer xenograft model showed that the DPP4 gene was down-regulated during the progression to castration-resistant prostate cancer, suggesting its tumor suppressive property." (PMID 32296640, 2020). "Consistent with our finding, CLDN3 was previously reported to express at a reduced level in EBVaGC, while DPP4 is an androgen receptor-induced tumor suppressor gene that was downregulated in some cases of prostate cancer." (PMID 32841292, 2020). "For example, suppression or down-regulation of DPP4 promotes prostate cancer progression via reduced degradation of its substrate CXCL12, leading to enhanced signalling via CXCR4 and increased invasion and metastatic spread to peripheral organs in vivo." (PMID 33143089, 2020). "The survival advantage shown in patients with prostate cancer taking DPP4 inhibitors only (HR 0.77; 95% CI: 0.64–0.93; P = 0.005) shows the benefit independent of metformin." (PMID 32296640, 2020). "Notably, CD26/DPP-4 activity is approximately twice as high in prostate cancer tissue as in benign prostatic tissue, potentially contributing to tumor growth." (PMID 40282969, 2025). "In the localized stage of prostate cancer, DPP4 activity may be relatively high, while in advanced metastatic disease, its activity can be reduced." (PMID 40766751, 2025). "Further DPP4 and PI3k/Akt pathway in prostate cancer is an area of ongoing research." (PMID 40766751, 2025). "Two CD26 forms were detected in mice, and we found two mRNAs in humans, but we do not know if these or the genetic variants of DPP4 (which were linked to clinicopathologic development of prostate cancer) are involved in these differences." (PMID 39001488, 2024). "However, in prostate cancer tissue expression of DPP-4 is significantly doubled, with inversion of TZ/PZ ratio." (PMID 33921222, 2021). "Multiway regulatory function of DPP-4 impels to hypothesis about its possible suppressing or promoting impact on cancers including prostate cancer." (PMID 33921222, 2021).
prostate carcinoma (continued). "Early cell lines and animal studies on prostate cancer showed that increased expression of DPP-4 may play an important role as a factor suppressing the long-period progression of the disease." (PMID 33921222, 2021). "DPP4 and PAX5 are significantly associated with the prognosis of prostate cancer patients." (PMID 33407865, 2021). "Taken all together, the blockage of DPP4 could have resulted in improved survival in prostate cancer patients in our analysis." (PMID 32296640, 2020). "Furthermore, soluble low DPP4 level has been suggested to be a prognostic biomarker for colorectal and prostate cancers as well as NSCLC malignant pleural effusions." (PMID 32055239, 2020). "On the other hand, DPP-4 may inhibit the malignant phenotype of prostate cancer cells via the blockade of the signaling pathway of basic fibroblast growth factor and the serum activity of DPP-4 is reduced in patients with metastatic prostate cancer." (PMID 27661113, 2017). "Furthermore, studies suggest that DPP4 may act as a tumor suppressor gene in the AR pathway, and its inhibition could potentially accelerate prostate cancer progression, particularly after androgen deprivation therapy." (PMID 40766751, 2025). "Moreover, our results showing the capability of ARV p17 to block FGF-2-induced angiogenesis through the involvement of DPP4 are in line with the previous studies showing the ability of DPP4 to inhibit the malignant phenotype of prostate cancer cells by blocking FGF-2 signaling." (PMID 33525607, 2021). "Moreover, DPP4/CD26 is detectable on many types of cancer cells; examples include thyroid carcinoma, gastrointestinal stromal tumor, prostate carcinoma, lung carcinoma, hepatic cancer, colon carcinoma, renal cell cancer (RCC), and malignant pleural mesothelioma (MPM)." (PMID 31792328, 2019). "Therefore, inhibition of DPP-4 may potentially trigger prostate cancer cell growth and metastasis, as shown in an in vitro and in vivo metastasis study." (PMID 27661113, 2017). "Cox proportional hazards models were used to estimate hazard ratios (HRs) and 95% confidence intervals (CIs) of incident prostate cancer-by-proxy, comparing SGLT2 inhibitors use with DPP4 inhibitors use." (PMID 39168098, 2024). "A positive correlation was noticed between DPP4/CD26 and MMP9 dosage in 40% pSS saliva samples, a connection that has already been reported in prostate cancer." (PMID 34220840, 2021). "In conclusion, use of CD26/DPP4 inhibitors is associated with improved survival outcomes in patients with prostate cancer but not in breast or pancreatic cancer patients, which may be linked to the protein expression profiling of CD26/DPP4 in these malignancies." (PMID 32296640, 2020). "Analysis of 906 subjects: 453 with metastatic PC and matched same-number control group (based on propensity score matching) displayed no coincidence between the development of prostate cancer metastases and DPP-4 inhibitor use." (PMID 33921222, 2021). "Furthermore, DPP4 levels correlated with prostate-specific antigen (PSA) level, residual tumor, tumor size, and stage in prostate cancer." (PMID 34055551, 2021). "Notably, one group of genes with very strong negative correlations (≤-0.9) to radiomic features were found to be associated with the AR signaling genes: KLK2, KLK3, HOMER2, BMPR1B, or belong to validated prostate cancer classifiers: CHRNA2, MT1H, DPP4, MYBPC1." (PMID 27438142, 2016). "The role of CD26/DPP4 in prostate cancer is not yet well-understood." (PMID 32296640, 2020). "Moreover, CD26/DPP4 biochemical activity was found to be twice as high in prostate cancer compared to benign prostate hyperplasia tissues, which could be a responsible factor for the growth of prostate cancer cells." (PMID 32296640, 2020).
prostate carcinoma (continued). "Despite prior literature indicating survival benefit of DPP4 inhibitors in prostate cancer, our study did not identify a statistically significant improvement of PFS in diabetic patients with advanced prostate cancer." (PMID 34055551, 2021).
hepatocellular carcinoma (49 papers, 2013 to 2025). A malignant tumor that arises from hepatocytes. "Although one study showed that thiazolidinediones reduce the risk of hepatocellular carcinoma and hepatic events in diabetic patients with chronic hepatitis B infection, there are relatively few on DPP-4 inhibitors in this group patient." (PMID 36831491, 2023). "For example, DPP4 transcripts from hepatocellular carcinoma (HCC) were significantly increased and were associated with a significantly larger tumour size." (PMID 37533175, 2023). "For instance, loss or alteration of Dpp4 expression is linked to the development of cancers, including breast, prostate, lung, ovarian and hepatocellular cancer and melanoma, and plays a key role in tumorigenesis and metastasis." (PMID 24244554, 2013). "Previous data refer to the role of DPP-4 in the development of various chronic liver diseases like non-alcoholic fatty liver disease, hepatitis C virus infection and hepatocellular carcinoma." (PMID 40786041, 2025). "Dysregulated DPP-4 expression was reported in various malignant tumors such as hepatocellular carcinoma." (PMID 40786041, 2025). "Hepatocellular carcinoma: Dipeptidyl peptidase 4 (DPP4) is a key protein that maintains intracellular iron accumulation and LPO." (PMID 38072908, 2023). "By analogy, DPP4 is shed from the surface of CD4+ T cells by kallikrein-related peptidase 5 (KLK5), and in hepatoma cells Serpin B3 induces overexpression of inactive DPP4." (PMID 33143089, 2020). "It has been also reported in hepatoma cells that Serpin B3 induces overexpression of inactive DPP4." (PMID 39001488, 2024). "Additionally, in hepatocellular carcinoma cell resistance-related studies, circMET,can drive hepatocellular carcinoma immunosuppression and anti-PD-1 therapy resistance via the miR-30-5p/Snail/DPP4 axis." (PMID 35615158, 2022). "Aberrantly high levels of DPP4 expression occurred in human hepatocellular carcinoma." (PMID 35267472, 2022). "Moreover, DPP4 inhibition with vildagliptin was also found to significantly reduce liver metastatic foci and metastatic index in a high fat diet-induced model of hepatocellular carcinoma." (PMID 33513866, 2021). "Dipeptidyl peptidase‐4 (DPP‐4), also known as CD26, is highly expressed throughout the body and plays a critical role in the development of chronic liver diseases, including those caused by hepatitis C virus infection, metabolic dysfunction‐associated steatohepatitis and hepatocellular carcinoma." (PMID 40344298, 2025). "More recently, a large Scandinavian cohort comparing GLP‐1 RAs with DPP‐4 inhibitors reported a lower risk of serious liver events (adjusted HR 0.85 [0.75–0.97]), driven by reduced cirrhosis, with no clear effect on hepatocellular carcinoma (HR 1.05 [0.80–1.39])." (PMID 40980971, 2025). "The role of DPP-4 and its inhibition have also been studied in the context of Hepatocellular Carcinoma (HCC)." (PMID 38611003, 2024). "Evidence from hepatocellular carcinoma (HCC) showed that both gene ablation and pharmacological inhibition of DPP-4 notably prevent tumor progression by down-regulating the production of chemokine CCL2." (PMID 35933633, 2022). "The mRNA expression of the dipeptidyl peptidase 4 (DPP4) gene family is highly upregulated in human hepatocellular carcinoma (HCC) and is associated with poor survival in HCC patients." (PMID 34771657, 2021). "This study reported, for the first time, on the expression and activity of the dipeptidyl peptidase 4 (DPP4) family during the development of hepatocellular carcinoma (HCC)." (PMID 34771657, 2021). "This study aimed to explore the prognostic role of dipeptidyl peptidase 4 (DPP4) expression in hepatocellular carcinoma (HCC)." (PMID 32294701, 2020). "DPP4 has been shown to regulate C-X-C motif chemokine ligand 10 (CXCL10)-mediated lymphocyte migration in mouse melanoma- and hepatocellular carcinoma-transplanted tumors." (PMID 37115489, 2023).
hepatocellular carcinoma (continued). "DPP4 is expressed on numerous tumors, including malignant pleural mesothelioma (MPM), renal cell carcinoma (RCC), gastrointestinal stromal tumor (GIST), hepatocellular carcinoma (HCC), and colorectal, lung, prostate, and ovarian cancer." (PMID 34055551, 2021).
colon carcinoma (43 papers, 2011 to 2025). "DPP4 overexpression is linked to prolonged survival of patients with mesothelioma, is hypermethylated and downregulated in cervical cancer, and seems to be regulated by C-myc in colon cancer." (PMID 32552834, 2020). "Altered DPP4 activity has been correlated with numerous tumors and administration of approved DPP4 inhibitors to experimental animals appeared to limit colon cancer or lung metastasis." (PMID 39861115, 2025). "Dipeptidyl peptidase 4 (DPP4) attaches to NOX1 in colon tumors to initiate ROS formation, which encourages ferroptosis." (PMID 38515787, 2024). "We established an unbiased CRISPR-Cas9-loss-of-function screen to define factors involved in surface targeting of the apical model cargo DPP4 in the enterocyte like colon carcinoma cell line, CaCo2." (PMID 36661306, 2023). "CD26 and/or dipeptidyl peptidase 4 inhibitors can prevent colon cancer and lung metastasis in animal models, although epidemiological studies in humans are not clear." (PMID 31285270, 2019). "Interestingly, it was reported that while the expression of DPP4 is low in the normal adult colon, DPP4 is highly expressed in some colon cancers and cancer cell lines." (PMID 33182266, 2020). "In vivo tumor-transplant models showed that the DPP4 inhibitor sitagliptin reduced tumor growth through the preservation of bioactive CXCL10 in the TME of melanoma and colon carcinoma." (PMID 33757558, 2021). "Ultimately, based on our MCIA, we identified CD15, CD104 (Integrin-β4), CD324 (E-cadherin), CD326 (EpCAM), and CD49f as biomarkers for colon cancer and CD24, CD26 (DPP4), CD106 (VCAM1), TIM-1, SSEA-3 (B3GALT5), SSEA-4 (TMCC1), TRA-1-60-R (PODXL) and EGFR for renal cancer." (PMID 36221114, 2022). "Barreira da Silva and colleagues have shown that DPP-4 inhibition preserved the active form of chemokine CXCL10, which enhanced T-cell accumulation and immunity, resulting in diminished growth of murine melanoma and colon cancer." (PMID 36860286, 2021).